H19 (H19 imprinted maternally expressed transcript)
Diseases named in the same sentence as H19 in open-access papers (continued):
Sharing a sentence is not in itself a finding about the gene and the disease.
cancer (continued). "Hypermethylation can occur in lncRNAs; metformin has been shown to decrease H19 levels by inducing H19 methylation, which has been reported in cancer cells and in animal models of pre-eclampsia." (PMID 38053839, 2023). "H19 and its intragenic miRNA-675 have been, together, studied in a plethora of cancers: colorectal, breast, glioma, rhabdomyosarcoma, gastric cancer, and liver cancer." (PMID 37716920, 2023). "The H19 gene has been suggested to play a role in cancer pathogenesis and is involved in genetic syndromes, as well as in maternal epigenetics and fetal and neonatal growth." (PMID 37810933, 2023). "Previous serological studies have also identified potential lncRNA signatures in Hp-infected cancer cells like H19, LINC00152, lncRNA AF147447, RP11-169F17.1, and RP11-669 N7.2." (PMID 37153158, 2023). "The plasma expression of H19 was significantly higher, and hence was presented as a useful marker in non-small cell lung and gastric cancers." (PMID 37189829, 2023). "All this evidence shows that metformin decreases H19 in different cancers, and the pivotal role of H19 in EOC supports further metformin research as a relevant H19-targeting therapeutic agent in OC." (PMID 38004379, 2023). "LncRNA H19 has been widely investigated as a biomarker and therapeutic target in various types of cancers including HCC." (PMID 37744274, 2023). "Among the 5 upregulated lncRNAs, H19 and Hotair have been reported as upregulation as well as scaffolds for Ezh2 in cancer cells." (PMID 37198149, 2023). "Aberrant expression levels of H19 were identified in different cancer types, including BC, where it acts as an oncogenic factor." (PMID 36674656, 2023). "A number of research have shown that the expression of lncRNA H19 (H19) in cancer cell lines and samples of patients with cancer is significantly upregulated." (PMID 35345660, 2022). "In conclusion, resveratrol inhibited cancer cell survival, while knockdown of lncRNA H19 resulted in increased sensitivity to resveratrol therapy." (PMID 35166018, 2022). "Likely, the exact effect of H19 on EMT in cancers and fibrotic diseases is tissue- and time-dependent." (PMID 36010635, 2022). "H19 has been shown to be involved in and expressed in almost every form of human cancers at all stages of tumorigenesis." (PMID 36246634, 2022). "The BSP results suggested that the methylation rates of the H19 promoter in EBV-positive cancer cells were significantly higher compared with that in EBV-negative cancer cells." (PMID 35674441, 2022). "For instance, the well-known lncRNA H19 displays aberrant promoter hypomethylation in many different cancer-types, including bladder cancer, colorectal cancer, and oral squamous cell carcinoma." (PMID 36533073, 2022). "Some lncRNAs have been thoroughly studied, like H19, Metastasis associated lung adenocarcinoma transcript 1 (MALAT1), or HOX transcript antisense intergenic RNA (HOTAIR), are considered to be pan-cancer markers involving multiple diverse malignancy tissues." (PMID 35697671, 2022). "Among them, we and others attributed the LncRNA H19 and its intragenic miRNA miR675-5p an important role in promoting cancer onset and progression." (PMID 35596172, 2022). "Careful examination of some cell functions influenced by H19 is needed to provide more evidence for their impacts on cancer cells in the future." (PMID 36230902, 2022). "The results showed that H19 was highly expressed in EBV-negative compared with EBV-positive cancer cells." (PMID 35674441, 2022). "For instance, as one of the earliest discovered lncRNAs, H19 is overexpressed in many cancers and has been recognized as a multifunctional regulator." (PMID 35252200, 2022). "The lncRNA ANRIL is involved in cancers, diabetes, and cardiovascular disease, lncRNA H19 in atherosclerosis, coronary artery diseases, regulation in blood pressure, and cancer, lnc-NR2F in developmental disorders, and HOTAIR in cancers." (PMID 35378133, 2022).
cancer (continued). "A growing body of studies was conducted on the orchestrating role of H19 in various cancers in multiple settings, such as initiation, progression, and metastasis." (PMID 36010635, 2022). "The oncofetal H19 lncRNA, with relatively high evolutionary conservancy across species, is most abundantly enriched during embryonic stages and in cancer tissues." (PMID 36010635, 2022). "Long non-coding RNAs, H19 in particular, have been revealed as powerful protective factors in various types of cancer." (PMID 35955440, 2022). "Aberrant expression of H19 is involved in progression and metastasis in numerous cancer through regulating various of targeted genes." (PMID 36310592, 2022). "After knocking down the H19, the viability, invasion, and migration ability of cancer cell lines were significantly reduced." (PMID 35345660, 2022). "A study found that expression levels of H19 lncRNA in cancer tissues were significantly higher than those in adjacent tissues." (PMID 35686101, 2022). "Based on the TCGA data, we divided the patients with each cancer subtype into the high-expression and low-expression groups according to the level of H19 and analyzed the correlation of the H19 level with prognosis." (PMID 36090894, 2022). "By applying TIMER2, we analyzed the expression level of H19 across various cancer types, and the results also indicated that upregulation of H19 was obvious in STAD in comparison with other cancer subtypes." (PMID 36090894, 2022). "As a molecular sponge, H19 modulates the function of let-7 family miRNA to promote the development of cancers such as pancreatic ductal adenocarcinoma." (PMID 36246634, 2022). "In fact, we have previously shown that knockdown of H19 contributes to the increased sensitivity of cancer cells to pterostilbene (a dimethyl ether analog of resveratrol), reducing cell proliferation and invasiveness." (PMID 35166018, 2022). "It was reported that RES inhibited cancer cell survival, while the knockdown of lncRNA H19 resulted in increased sensitivity to RES therapy." (PMID 36704707, 2022). "Five metabolism-related lncRNAs (HAGLR, H19, AC092718.4, FAM181A-AS1, and AC007383.2) are associated with cancer." (PMID 36343057, 2022). "There was a study reported that H19, a Long Non-coding RNA, played an oncogenic role in pan-cancer including TGCT and showed that miRNA-mediated lncRNA-TF-gene co-regulation is complicated yet important in cancers." (PMID 35575252, 2022). "The expression levels of H19 were lower in EBV-positive compared with EBV-negative cancer cells; however, the expression of H19 was significantly upregulated after treatment with 5-Aza-CdR in EBV-positive cancer cells." (PMID 35674441, 2022). "The expression levels of genes related to the cell cycle, DNA replication, EMT, GC, and cancer pathways were positively correlated with the expression level of H19." (PMID 36090894, 2022). "H19 controlled the key processes in malignant transformation and cancer progression, including cancer cell proliferation, migration, invasion, and EMT process." (PMID 35656022, 2022). "We observed a significantly higher methylation rate of the H19 promoter region in EBV-positive cancer cells compared with that in EBV-negative cancer cells." (PMID 35674441, 2022). "H19, especially, which has been the subject of about 60 recent publications linked to EMT in cancer, was found to be attenuated in tamoxifen-resistant breast cancer cells after curcumin treatment." (PMID 35873564, 2022). "Researchers have so far confirmed several important roles that H19 plays in drug resistance of various cancers." (PMID 36246634, 2022). "Along with the development of relevant studies, H19 has been testified to function in the tumorigenesis and drug resistance in human cancers via different mechanisms." (PMID 36246634, 2022). "LncRNA H19 (H19) is located on human chromosome 11p15.5, and its role in cancer progression is still controversial." (PMID 35565245, 2022).
cancer (continued). "Some lncRNAs act as “microRNA-sponges” to compete with mRNAs for microRNA binding, which reduce recognition rate and biological activity of microRNA consequently, while modulate the progression of cancers, such as H19, HOTAIR, MALAT1, and XIST." (PMID 35697671, 2022). "The regulation of miR-675 by H19 is illustrated to be responsible for limiting placental growth before birth and the progression of different Cancers." (PMID 36246634, 2022). "Functional assays in both ER(+)-MCF-7 and ER(-)-Triple negative breast cancer (TNBC) carcinomas have shown that acquisition of resistance to PTX requires the upregulation of H19, which in turn blocks activation of several apoptotic pathways." (PMID 35955440, 2022). "H19 exerts its regulatory function in several types of cancer via regulating several oncogenic signaling pathway." (PMID 34977037, 2021). "H19 was characterised in several cancers as being oncogenic and a promoter of metastasis but its mechanisms of action were only partially elucidated." (PMID 33799834, 2021). "In particular, we analyzed, by Droplet Digital PCR (ddPCR), six cancer-associated lncRNAs (MALAT1, NEAT1, HOTAIR, H19, PVT1, MEG3) in both FNAs and surgical tissues." (PMID 33030666, 2021). "H19 has been confirmed to be up-regulated in many cancers and promotes the proliferation of cancer cells." (PMID 34583640, 2021). "Since H19 lncRNA is involved in many biological pathways related to tumorigenesis, we sought to develop a non-cancer lineage with CRISPR-Cas9-mediated H19 knockdown (H19-) and observe the changes in a cellular context." (PMID 34526543, 2021). "By choosing H19 as strongest sulforaphane-regulated candidate lncRNA, we were able to mimic the well-known cancer inhibitory effect of sulforaphane by siRNA-mediated downregulation of H19." (PMID 33669381, 2021). "H19 regulates the expression of some cancer-related proteins, such as the ubiquitin ligase E3 family, calneuron 1 and retinoblastoma tumor suppressor (RB1), and alpha-4, beta-3, and beta-5 integrins." (PMID 34204445, 2021). "We observed that H19 downregulation in the non-cancer cell line promotes cell growth and morphological alterations, like increased cell volume and intracellular granularity and cell cycle arrest in the G2/M phase, without changes in viability." (PMID 34526543, 2021). "Several recent studies have identified abnormal expression of H19 in various human cancers, such as colorectal, liver, gastric, pancreatic, esophageal, breast, lung, glioma, ovarian, and hematological cancers." (PMID 33402118, 2021). "In this review, we discussed the key roles of H19 in cancer development and progression via its regulatory function in several oncogenic signaling pathways, such as PI3K/Akt, canonical Wnt/β-catenin, canonical NF-κB, MAPK, JAK/STAT and apoptosis." (PMID 34977037, 2021). "Previous studies have shown that abnormal H19 expression is involved in many pathological processes, such as cancer, mainly through sponging miRNAs, interacting with proteins, or regulating epigenetic modifications." (PMID 34977037, 2021). "It was demonstrated that aspirin (5 mM) treatment regulates E2-induced cancer stem-like by downregulation of H19 and ERβ expression in mice." (PMID 34926688, 2021). "H19 can also affect cancer cell metabolism, through the sponging effect of miR-324-5p, which regulates PKM2, a major contributor to the Warburg effect." (PMID 34680193, 2021). "Both A549 and H460 cancer cells were transfected with the NC plasmid, lncRNA H19 overexpression plasmid or both the lncRNA H19 overexpression plasmid and the miR-130a-3p mimic, and were then exposed to 6 Gy X-ray irradiation." (PMID 34863180, 2021). "The only exception was the long non-coding RNA (lncRNA) H19, which is frequently reported as dysregulated in cancer including HCC, sometimes up- and sometimes downregulated." (PMID 33541355, 2021).
cancer (continued). "To observe the role of lncRNA H19 in cancer initiation we sought to develop a non-cancer knockdown murine cell line." (PMID 34526543, 2021). "Investigating the human form of H19 more deeply revealed numerous cancer-related SNPs, with ~55% (12/22) being PCa related and 43 different TFs, within 23 TF families across 41 different tissue/organs capable of binding to its promoter." (PMID 34934057, 2021). "H19 plays differential roles in regulating biological processes in a variety of different types of cancer cells." (PMID 34977037, 2021). "For instance, H19 is involved in tumourigenesis and cancer progression in both haematological and solid cancers." (PMID 33799834, 2021). "Three thyroid-specific genes (TG, TPO, and NIS), six cancer-associated lncRNAs (MALAT1, NEAT1, HOTAIR, H19, PVT1, MEG3), and two housekeeping genes (GAPDH and P0) were analyzed using Droplet Digital PCR (ddPCR)." (PMID 33030666, 2021). "The current research results suggest that H19 was abnormally expressed in various malignant tumors and had proto-carcinogenic activity." (PMID 33403385, 2021). "H19 was the first molecule to be identified as lncRNAs; since then, its role in various cancers has been established." (PMID 35011635, 2021). "First, the expression of the lncRNA H19 was downregulated after siRNA transfection in both A549 and H460 cancer cells." (PMID 34863180, 2021). "Meanwhile, contributions have been made in plenty of studies retrieved in our article to testified the possibility of H19 SNPs in diagnosis and individualized treatment of various cancer." (PMID 34310645, 2021). "The long noncoding RNA H19 is increased in most cancers as well as in chronically inflamed liver and in a subclass of highly proliferative HCC tumors." (PMID 33499244, 2021). "Abnormal over-expression of H19 has been noted in many types of cancer, and accumulating evidence indicated that H19 is involved in cancer initiation, progression, and metastasis." (PMID 33800276, 2021). "Recently, H19, as a cancer-promotive gene in MM that acts on the NF-κB signaling pathway, was investigated." (PMID 34977037, 2021). "Studies have shown that the expression of H19 in some types of cancers like colon, bladder, and breast cancer is high." (PMID 34337048, 2021). "It was demonstrated that aspirin (5 mM) reduced glycolysis, glucose uptake, lactate production, ATP levels, and stem-like cancer feature by inhibiting both H19 and PDK1 in MDA-MB-231 and MCF-7 cells." (PMID 34926688, 2021). "In EC, the overexpressed lncRNA H19 promoted cancer cell proliferation considering fresh EC tissues of 43 cases from July 2010 to July 2012 via upregulating the expression of the HOXA10 gene by competitively targeting and downregulating miR-612 expression." (PMID 34885213, 2021). "Recent studies indicate that H19 is dysregulated in various cancer types and serves as oncogene or tumor suppressor to affect the development and progression of cancer through various mechanisms." (PMID 34760707, 2021). "Our results also agree with in vitro studies that demonstrated an important role for H19 in regulating EMT in cancer cells." (PMID 34402430, 2021). "H19, one of the major cancer genes, is highly expressed in almost all cancers and participates in all phases of tumourigenesis." (PMID 34034760, 2021). "In cancer progression, lncRNA H19 exerted a positive function on the activation of NF-κB signaling pathway." (PMID 33708438, 2021). "Recently, lncRNA H19 (H19) became a research focus due to its ectopic expression in human malignant tumors, where it functioned as an oncogene." (PMID 34421359, 2021). "H19 can then activate the β-catenin pathway by acting as a ceRNA to sponge miR-141, thus increasing drug resistance in cancer cells." (PMID 34778084, 2021). "In this review, we summarize the abnormal overexpression of H19 in human cancers, which suggests wide prospects for further research into the diagnosis and treatment of cancers." (PMID 34421359, 2021).
cancer (continued). "LncRNA H19 is a widely investigated lncRNA that plays an important role in the regulation of stem cell differentiation and cancer cell growth, and is also a known driver of uterine leiomyomas." (PMID 33881140, 2021). "H19 contains usual and unusual binding sites for the let-7 family of microRNAs that has a significant role in cancer and metabolism." (PMID 34337048, 2021). "Even in the same cancer, H19 also sponges various microRNAs to mediate diverse regulatory mechanisms." (PMID 34250088, 2021). "Previous studies suggest that H19 is a cancer promoter, which is not only highly expressed in PDAC, but also in cancer of the breast, stomach, colon and rectum." (PMID 33669381, 2021). "BC-819, a DNA plasmid, is a potential therapeutic approach for cancers that overexpress the H19 gene." (PMID 34863180, 2021). "Increasing evidence has demonstrated the important role of oncogenic long noncoding RNA H19 in various cancers, including EOC." (PMID 34475985, 2021). "Cancer-associated fibroblasts (CAFs) are the main type of stromal cells in the CRC tissue matrix, which can transfer H19 into cancer cells by secreting H19-containing exosomes." (PMID 34778084, 2021). "Because the basal expression of the biological relevant cancer promoter H19 and its fold change of sulforaphane-induced downregulation were of highest relevance, we examined the mRNA levels of H19 in four other PDAC cell lines." (PMID 33669381, 2021). "In these previous analyses, H19 function was determined by transfecting cancer cells with H19-expression vectors and analyzing cell motility and gene expression." (PMID 34402430, 2021). "C-myc can directly regulate the lncRNA H19 to promote the proliferation of cancer cells and affect the prognosis of patients." (PMID 34930980, 2021). "LncRNA H19 as the first discovered classical regulator lncRNA is involved in the regulation of multiple cancers, including GBM." (PMID 34899682, 2021). "By competitively binding with miR-140, a variety of lncRNAs, such as lncRNA XIST, lncRNA MALAT1 and lncRNA H19, can promote cancer progression via facilitating the proliferation, migration and invasion of cancer cells in vitro and metastasis in vivo." (PMID 34496800, 2021). "Several studies showed that H19 acts as an oncogene in various cancers, including CRC and its upregulation predicts poor prognosis in patients with CRC." (PMID 34484116, 2021). "Recently, the regulatory relationship between H19 and oncogenic signaling pathways in various types of cancer has been of great interest to many researchers." (PMID 34977037, 2021). "The aim of this manuscript was to summarize recent findings on H19 expression in cancer and to clarify the impact of imprinting on cancer." (PMID 34421359, 2021). "Examples of this are HOXD-AS1 and ZFAS1 function in invasion and metastasis, HULC in cell metabolism and proliferative signaling or H19 in both the maintenance of cancer stem cells and angiogenesis." (PMID 34071216, 2021). "Overexpression of H19 in cancer cell lines and sample patients and its oncogenic activities have been demonstrated by several studies." (PMID 34771549, 2021). "H19 plays a dual role of oncogene or tumor suppressor gene, depending on the cancer type and stage of development." (PMID 34199840, 2021). "The imprinted oncofetal lncRNA H19 is expressed in the embryo, downregulated at birth, and then reappears in tumors, with accumulating data supporting that H19 is one of the major genes in cancer." (PMID 34596120, 2021). "While not directly targeting an lncRNA, this is an interesting example of how ncRNAs properties, like H19 cancer-specific expression, can be harnessed for novel cancer therapeutic interventions." (PMID 34316694, 2021). "These oncogenic signaling pathways regulated by H19 are involved in cell proliferation, proliferation, migration and invasion, angiogenesis, and apoptosis of various cancer cells." (PMID 34977037, 2021).